TF (transferrin)
Diseases named in the same sentence as TF in open-access papers (continued):
Sharing a sentence is not in itself a finding about the gene and the disease.
anemia (continued). "Recent guidelines and recommendations on the treatment of HF-related anemia advocate IV iron for symptomatic patients (serum ferritin <100 μg/L, or ferritin between 100–299 μg/L and transferrin saturation (TSAT) <20%) to improve exercise capacity and quality of life." (PMID 31614529, 2019). "Hepcidin may also decrease serum transferrin levels and total iron binding capacity (TIBC), leading to functional iron deficiency and anemia." (PMID 30673726, 2019). "Amount of transferrin protein is an indicator of body response to anemia." (PMID 30161219, 2018). "Interestingly, this knock-in mouse model (Tfr2 KI), specifically lacking the Tfr2β-isoform (α+β0), is characterized by normal transferrin saturation, liver iron concentration, Hepc, and Bmp6 levels, but shows transient anemia at a young age." (PMID 30360575, 2018). "Anemia might be related higher non-transferrin-bound iron and labile plasma iron levels, leading to oxidative stress-mediated cardiac autonomic dysfunction, thus resulting in reduced HRV." (PMID 29515436, 2018). "Six cases with anemia had both serum ferritin < 30 μg/L and transferrin saturation < 12%." (PMID 28875005, 2017). "The aim of this study was to test hypothesis that transferrin, coinfluenced by inflammation, malnutrition, anemia, and oxidative stress, may better reflect global IBD patient's condition than any other more specific index." (PMID 29226154, 2017). "However, as a marker of anemia, defined by a drop in hemoglobin concentration, transferrin overall performance was bad." (PMID 29226154, 2017). "Low serum transferrin can disturb hemoglobin production, leading to anemia." (PMID 27651883, 2016). "Within a twelve-month data extraction period, the charts of 405 hospitalised patients aged 65–101 years were retrospectively analysed for IDA, defined according to WHO criteria for anaemia (haemoglobin: <13.0 g/dL (m)/<12.0 g/dL (f)) in conjunction with transferrin saturation <20%." (PMID 26236500, 2015). "Most importantly, the elevation of ferritin and transferrin correlated with the inflammatory state and anemia of chronic disease suggesting that hyperferritinemia could potentially play a role in regulating immunity." (PMID 22871034, 2012). "The risk for AVF failure associated with increasing RDW is likely not due to anemia, as neither hematocrit, hemoglobin, iron, transferrin nor ferritin levels affected AVF failure risk in univariable analysis or correlated with RDW." (PMID 22574168, 2012). "In addition, the saturation of transferrin of these seven women was below the threshold of 16%, indicating a marked anaemia." (PMID 21854590, 2011). "Inadequate provision of transferrin impairs hemoglobin production, thus leading to anemia." (PMID 21637603, 2010). "Anemia is characterized by low erythrocyte count or hemoglobin levels below recommended levels, while iron deficiency can occur without anemia and is indicated by low plasma ferritin and transferrin saturation (Özdemir, 2015)." (PMID 39479620, 2024). "Considering that an altered glycosylation and/or glycation of transferrin affects the metabolism of Fe, thus worsening anemia, the use of exclusively glucose-free dialysis solutions might be the therapy of choice for PD patients with poorly regulated anemia, which requires high doses of ESAs." (PMID 38731843, 2024). "We hypothesize that increased transferrin saturation is associated with increased mean cellular hemoglobin concentration (MCHC) which in turn is associated with decreased red cell counts and worsening anemia." (PMID 39659429, 2024). "This aligns with existing literature emphasizing the increased susceptibility to anemia in CKD patients due to factors such as erythropoietin deficiency, iron metabolism disturbances, and chronic inflammation induced by renal dysfunction leading to alterations in ferritin, hepcidin, and transferrin." (PMID 39109107, 2024).
anemia (continued). "This disparity may be attributed to higher rates of anemia, lower mean corpuscular volume, and lower serum transferrin saturation in this population, suggesting that racial or genetic heterogeneity might contribute to the likelihood of requiring blood transfusion." (PMID 38509493, 2024). "Also, some data that may affect anemia and hyperphosphatemia such as diet, lifestyle, ferritin, transferrin saturation, and levels of B12 and B9 were incomplete." (PMID 37363538, 2023). "Notably, some ALD cases may show anemia, and this could be due to erythropoiesis disruption or gastrointestinal bleeding in cases of alcohol-induced cirrhosis or reduced serum transferrin." (PMID 36214835, 2022). "The BMI values were negatively correlated with the levels of anemia biomarkers (mean corpuscular volume, mean corpuscular hemoglobin, and transferrin saturation) in non-pregnant women aged 25–49 years in South Africa, suggesting that obesity was associated with a higher risk of anemia." (PMID 35627766, 2022). "Patients without anaemia undergoing elective cardiac surgery will be allocated to an iron-deficient and an iron-replete group based on standard pre-operative blood tests (ferritin, transferrin saturation and C-reactive protein)." (PMID 35130975, 2022). "Additionally, we wanted to measure the impact of this system in the ordering of most common anaemia related tests such as ferritin, transferrin, total iron, folate and vitamin B12 in order to know if it is also a good strategy for test management and cost savings." (PMID 33927552, 2021). "Previous studies showed that female gender, history of diabetes mellitus, CKD stage, serum transferrin saturation, serum levels of ferritin and iPTH and angiotensin-converting enzyme inhibitors (ACEI) or angiotensin receptor blocking agent (ARB) were risk factors for severe anemia in CKD patients." (PMID 32240223, 2020). "In theory, sTfR measurement may be the most important biomarker to explain the etiology of anaemia in MM compared to more established biomarkers, such as serum ferritin, transferrin saturation, ferritin index (sTfR/log transferrin saturation), hypochromic reticulocytes and C-reactive protein (CRP)." (PMID 31683939, 2019). "Hepcidin concentrations have been shown to predict nonresponsiveness to oral iron therapy; and in combination with other iron biomarkers such as ferritin and/or transferrin, hepcidin may guide in whom and when iron-based anemia interventions may be ineffective." (PMID 25904736, 2015). "Peripheral blood analysis revealed an anaemia of chronic disease with hemoglobin of 108 g/L (norm - male 130 - 175 g/L), serum iron 2 μmol/L (norm 10 - 30 μmol/L), transferrin 1.4 g/L (2 - 3.5 g/L), transferrin saturation 6% (norm 16 - 50%) and ferritin 354 μg/L (norm 20 - 500 μg/L)." (PMID 21693070, 2011). "Vadadustat increases iron availability compared with darbepoetin in DD‐CKD–related anemia, as increased serum transferrin (measured as TIBC) is accompanied by decreased transferrin saturation, serum hepcidin, and serum ferritin." (PMID 41376433, 2026). "Anemia was deemed to be iron responsive in all cases, with a median (IQR) transferrin saturation of 12.0% (8.0%-18.5%)." (PMID 40152861, 2025). "We show that pegcetacoplan improves biomarkers of iron overload, including reduced transferrin saturation, increased hepcidin concentrations, and decreased ARCs, by blocking both IVH and EVH and preventing anemia." (PMID 41155315, 2025). "Iron metabolism markers, such as transferrin saturation (TSAT) and ferritin, are crucial in anemia management in patients with CKD and those undergoing dialysis, yet optimal levels remain unelucidated." (PMID 40290139, 2025). "For individuals with CKD and anemia, KDIGO suggests a goal transferrin saturation (TSAT) of 20% to 30% and ferritin levels of 100 to 500 ng/ml." (PMID 39958087, 2025).
anemia (continued). "Reduced serum iron and transferrin, accompanied by increased ferritin, TIBC, and UIBC, reflect a classic anemia of inflammation profile." (PMID 41012793, 2025). "DSS treatment resulted in significant reductions in RBC count, HCT, and HGB levels, indicating the development of anemia, along with a decrease in serum iron, UIBC, and TF levels." (PMID 39940407, 2025). "Altered lymphocyte count, serum albumin, and transferrin levels is common among individuals undergoing TKA, particularly in older patients, those with anemia, and individuals with normal or low weight." (PMID 40727701, 2025). "To investigate the relationships between transferrin saturation, MCHC, and anemia, we utilized a database of patients with SCD seen at the NIH between 2001 and 2015." (PMID 39659429, 2024). "Changes from baseline of the following anemia marker levels are considered: hemoglobin (Hb), hematocrit (Ht), plates (PLTS), reticulocytes, iron, ferritin, transferrin, and transferrin saturation." (PMID 39407947, 2024). "His iron panel showed normal serum ferritin and iron saturation but decreased transferrin and total iron-binding capacity (TIBC), which is consistent with anemia of chronic disease." (PMID 39280374, 2024). "Excessive urinary losses of iron, TF, EPO, transcobalamin, and/or copper in relation to anemia and its ineffectiveness after iron and EPO supplementation in nephrotic syndrome were extensively reviewed." (PMID 36855344, 2023). "Various RCTs have individually discovered that HIF-PHIs substantially benefit iron regulation in treating anemia by decreasing hepcidin, transferrin saturation (TSAT), and ferritin while increasing transferrin and total iron-binding capacity (TIBC)." (PMID 38021836, 2023). "The presented results showed an early decrease of iron, transferrin, and TSAT in AI patients upon the progression of the state of anemia, whereas ferritin and Hepc levels were increased in the AI population." (PMID 37046922, 2023). "In this study, the correlation between malnutrition, hypoalbuminemia, anemia, elevated CRP, and low transferrin levels, as well as mortality in seniors between 65 and 100 years, should be revealed." (PMID 37892441, 2023). "Both present with decreased circulating serum iron concentration and transferrin saturation, but while IDA is characterized by anemia with depleted iron stores (i.e. serum ferritin below the lower limit of normal), iron stores are ample in ACI." (PMID 37578340, 2023). "Patients with IRIDA present with hypochromic, microcytic anemia (hemoglobin 6–9 g/dL), very low MCV (45–65 fL) and transferrin saturation (<5%), suppressed oral iron absorption, and abnormal iron utilization in response to parenteral iron." (PMID 37578340, 2023). "The other iron indices to confirm the plasma expansion effects, such as serum iron, ferritin, transferrin, and total iron-binding capacity (TIBC) in this study, are limited as the blood investigations are only applicable to women with anemia during pregnancy." (PMID 37396129, 2023). "Although the prevalence of anemia is relatively high in developing countries like Ghana, we may not have explicitly considered all hematological parameters like haematocrit, RBCs, erythropoietin, total iron binding capacity, transferrin saturation and serum ferritin." (PMID 38318113, 2023). "In the group of children with AI and anemia, hepcidins levels were much higher compared to the other groups, including IBD, with inverse correlations to SI, transferrin and sTfR." (PMID 35177695, 2022). "Transferrin saturation which is the ratio of serum iron and TIBC, and therefore becomes very low at iron anemia, shows anti-correlation with the incidences of GHD with marginal statistical significance (OR = 0.85)." (PMID 36579561, 2022).
anemia (continued). "A preoperative Hb level ≤ 10 mg/dL (odds ratio [OR], 20.1; 95% confidence interval [CI], 4.71–125, p < 0.001) and transferrin saturation (TSAT) < 25% (OR, 12.8; 95% CI, 2.51–129, p < 0.001) were predictors for anemia improvement." (PMID 36142295, 2022). "It is possible that the anaemia observed in DR-TB patients is due to nutritional iron deficiency and not chronic disease, however this study did not explore levels of iron, ferritin, hepcidin and transferrin in TB patients or assess haemoglobin levels in the general population." (PMID 36490236, 2022). "Anaemia was present in 84 (46.4%) patients with advanced CKD including 30 (16.6%) patients who had low transferrin levels, while 34 (25.9%) patients with early CKD had anemia." (PMID 36121812, 2022). "Transferrin (Tf) showed a critical role in the upregulation of hepcidin (HAMP) gene expression, degradation of Fpn in liver Küpffer cells, and correction of anaemia by Tf treatment in Hbb th1/th1 mice." (PMID 34281283, 2021). "To evaluate whether transferrin correlation with CDAI or RI truly reflects its association with the disease severity and is not mediated by transferrin association with inflammatory, nutritional, and anemia indices or antioxidants, we employed multiple regression." (PMID 29226154, 2017). "Multivariate Poisson regression analysis for anemia was performed after adjustment for gender, age, smoking, hypertension, DM, use of ESA, ferritin, transferrin, albumin, total cholesterol, and eGFR." (PMID 29077007, 2017). "The aim of our study was to evaluate transferrin levels in a large cohort of IBD patients and relate it to indices of inflammation, malnutrition, anemia, and oxidative stress." (PMID 29226154, 2017). "ID was defined as ≥2 of 3 abnormal iron indicators (low serum ferritin [SF], high free erythrocyte protoporphyrin [FEP], low % transferrin saturation [TSAT]); ID anemia (IDA) was defined as ID plus low hemoglobin (Hgb)." (PMID 24373608, 2013). "Anaemia was normocytic in 88.8%, and we observed: low serum iron in 46.3%, low ferritin 10.1%, high TIBC 2%, low % transferrin saturation (Tsat) 40%, and high sTfR 25%." (PMID 22611486, 2012). "The present study reveals urinary elevations in two key iron-binding proteins (ferritin and transferrin) in SLE patients, the levels of which were found to be correlated with each other, as well as with disease activity, inflammatory status and anemia." (PMID 22871034, 2012). "These mutations result in dysregulated levels or activity of hepcidin, leading to high iron-saturation of transferrin followed by progressive liver iron accumulation in the absence of anaemia." (PMID 41882292, 2026). "The assessment of anemia and renal dysfunction severity was limited, as additional markers such as ferritin, transferrin saturation, and proteinuria were not included in the analysis." (PMID 40283684, 2025). "Our analysis did not encompass outcomes such as quality of life, changes in baseline ferritin and transferrin saturation, and the prevalence of preoperative, intraoperative, and postoperative anemia, as these data were not reported in the included studies." (PMID 39649896, 2024). "Additionally, the biochemical triad of microcytic anemia, elevated serum ferritin, and decreased transferrin saturation is suggestive of ACP, particularly after ruling out more common conditions like thalassemia and anemia of inflammation." (PMID 40729217, 2024). "The limitation of this study is that it was an observational study of guideline-based anemia management with darbepoetin alfa rather than a randomized controlled trial (RCT) with separate groups for transferrin saturation management goals." (PMID 38941000, 2024). "Considering that anemia in PCM is, in general, an AI, the analysis of ferritin and transferrin saturation is recommended before starting iron supplementation since it can be harmful to the patient by favoring fungal growth, which depends on iron for its metabolism." (PMID 38786672, 2024).
anemia (continued). "Compared to iron sucrose for anemia, iron isomaltoside demonstrated comparable Hb responder (SMD=1.41; 95% CI=0.71 to 2.81; P=0.33), serum ferritin (SMD=15.13; 95% CI=-23.45 to 53.71; P=0.44), transferrin saturation (SMD=1.20; 95% CI=-1.08 to 3.47; P=0.30)." (PMID 38357109, 2023). "In the current study, we are unavailable to obtain the anemia-related indexes such as serum Fe and transferrin saturation between children with obesity and without obesity." (PMID 38150411, 2023). "Second, we did not assess serum iron, ferritin, or transferrin levels, which are further anemia indicators." (PMID 37273341, 2023). "For patients with anemia without iron therapy or for patients who need erythropoiesis-stimulating agents, a transferrin saturation ≤30% and serum ferritin ≤500 ng/mL are indicated by KDIGO guidelines as setting points for iron supplementation." (PMID 37374094, 2023). "Therefore, the levels of serum ferritin, transferrin saturation, vitamin B12, and folic acid should be monitored regularly in CKD patients with anemia." (PMID 36799117, 2023). "They include normocytic normochromic anemia, and low SI with no concomitant increase in transferrin or sTfR." (PMID 35177695, 2022). "Although only a smaller proportion of the female participants showed clear signs of anemia such as reduced hemoglobin (11%) or MCV (21%) levels, more than half of the women showed serum ferritin levels and a transferrin saturation indicative of decreased iron stores and an insufficient iron intake." (PMID 36447164, 2022). "We defined IO phenotypes as a) elevated serum ferritin (SF) and transferrin saturation (TS) at screening and CE, and b) absence of IO treatment, anemia, transfusion >10 units, alcohol intake >30 g/d, hepatitis B or C, and pregnancy." (PMID 35895739, 2022). "Anemia in CD is considered IDA because of iron malabsorption, and laboratory findings are usually consistent with ID, which means low SI and ferritin, and high transferrin levels." (PMID 35177695, 2022). "Although iron, transferrin, RBC counts, haemoglobin and haematocrit percentage were slightly reduced, the magnitude of this change was not enough to cause anaemia." (PMID 36014924, 2022). "Second, indicators of iron storage, such as serum ferritin and transferrin, were not measured in this study; this led to difficulties in identifying types of childhood anemia." (PMID 35807821, 2022). "We defined IO phenotypes as a) elevated serum ferritin (SF) and elevated transferrin saturation (TS) in both screening and CE, and b) absence of IO treatment, anemia, transfusion >10 units, alcohol intake >30 g/d, hepatitis B or C, and pregnancy." (PMID 35895739, 2022). "To rule out the putative role of iron status, we also measured transferrin and soluble transferrin receptor in order to discard subclinical anemia due to higher hepcidin on the one hand, and iron overload on the other." (PMID 34065056, 2021). "For example, take the negative relation instance “Daily CBC show anemia ([Hbg]e1 8.7 - 8.8, current at 8.7), with low Fe, transferrin+TIBC wnl, high ferritin." (PMID 34255697, 2021). "The incidence of microcytosis in these studies is very variable (42–87.7%) and it has been observed in the absence of anaemia or reduced transferrin saturation." (PMID 33464144, 2021). "The classical features of IRIDA patients are: increased plasma hepcidin levels, moderate/severe anemia (Hemoglobin (Hb) 6–9 g/dl), hypochromic, microcytic anemia (MCV 45–65 fL), low transferrin saturation (<5%), normal or even moderately elevated serum ferritin level, normal C‐reactive protein." (PMID 34343368, 2021). "Although we have also observed a decline in its demand, it has not been as significant as total iron or transferrin given that ferritin was also included in the “Microcytic Anaemia Follow Up” clinical profile." (PMID 33927552, 2021).